CD47 (CD47 molecule)
Diseases named in the same sentence as CD47 in open-access papers (continued):
Sharing a sentence is not in itself a finding about the gene and the disease.
breast carcinoma (continued). "Overexpression of CD47 has been found in a number of tumors, such as acute myeloid leukemia, non-small cell lung cancer, bladder cancer, non-Hodgkin’s lymphoma, and breast cancer." (PMID 30061885, 2018). "In this study, we first assessed the expression levels of CD47 in various breast cancer cell lines using FACS." (PMID 30463284, 2018). "As a result of its previous preclinical and clinical success for tumor targeting, we believe CD47 antibody has the potential to be labeled with our SERS nanoparticles for effective targeting of breast cancer." (PMID 30463284, 2018). "In another study, CD47 expression in breast cancer cells was shown to be enhanced by the TNF-NF-κB1 inflammatory pathway, and its inhibition by blocking antibodies increased the recruitment of the innate immune system and phagocytosis." (PMID 30213113, 2018). "Work by Zhang indicates that HIF-1α can stimulate CD47 expression, an important factor for maintaining plasticity of the cells, which also enables breast cancer cells to avoid phagocytosis by macrophages." (PMID 30301213, 2018). "Here, we explore the ability of SERS nanoparticles conjugated with a cluster of differentiation-47 (CD47) antibody to target breast cancer." (PMID 30463284, 2018). "Based on the analysis of datasets derived from thousands of primary tumors of breast cancer patients, CD47 expression was not only significantly correlated with patient survival but also correlated with the expression of HIF-1α targeting genes." (PMID 30061885, 2018). "Note the negatively expressing cell line, DLD−, shows little expression of CD47 whereas all the breast cancer cell lines show overexpression of CD47 to varying degrees." (PMID 30463284, 2018). "In a previous study, anti-CD47 antibody can inhibit breast cancer, bladder cancer, ovarian cancer, colorectal cancer, and glioblastoma growth as a monotherapy." (PMID 28484448, 2017). "Lastly in this report, we also demonstrate that blocking the TNF pathway, by using the antibody infliximab, increases phagocytosis of MCF7 breast cancer cells mediated by a reduction on CD47 expression." (PMID 28378740, 2017). "We place the CD47 candidate E6 enhancer in this category, even though it is located within the CD47 downstream breast cancer SE." (PMID 28378740, 2017). "Overall our data demonstrate for the first time that the TNF inflammatory pathway upregulates CD47 expression in breast cancer cells." (PMID 28378740, 2017). "Lastly, we blocked BRD4 binding to the CD47 breast cancer SE, by using the inhibitors I-BET151 and PFI-1 and we observed a reduction on TNF-α mediated CD47 upregulation in MCF7 cells." (PMID 28378740, 2017). "For instance, the breast cancer cell lines HCC1954 and MCF7 have a downstream SE associated with CD47, while T-ALL and DLBCL cancer cell lines have either enhancers or SEs upstream of the gene." (PMID 28378740, 2017). "Results also showed an association between co-expression of CD47 and GRP78 mRNA (z-score threshold ±2.0 fold mRNA) and reduced overall survival (OS) in breast cancer patients." (PMID 28815041, 2017). "We have now identified co-expression of GRP78 and CD47 as a novel biomarker predicting decreased overall survival and reduced therapeutic responsiveness in ER+ breast cancer." (PMID 28815041, 2017). "For example, hypoxia-inducible factor 1 (HIF-1) promotes CD47 expression in breast cancer cells under hypoxic conditions, whereas NF-κB mediates the increase in CD47 in hepatocellular carcinoma." (PMID 29050218, 2017). "Our group previously showed that targeting GRP78 in breast cancer cells and tumors reduced the “don't eat me” signaling protein CD47 levels." (PMID 29113324, 2017). "Expression of B6H12-responsive genes correlated with CD47 mRNA expression in human breast cancers, suggesting that the CD47 signaling pathways identified in breast CSCs are functional in vivo." (PMID 26840086, 2016).
breast carcinoma (continued). "In summary, these data demonstrate that CD47 is an active signaling receptor in triple negative human breast carcinoma cells." (PMID 26840086, 2016). "We also observed a significant difference of CD47 protein levels between two groups of exosome samples derived from healthy people and age-matched breast cancer patients (p = 0.004)." (PMID 27819324, 2016). "Our studies show a differential CD47 expression in blood-derived individual circulating exosomes that is correlated with breast cancer status, demonstrating a great potential of individual exosome profiles in biomarker discovery." (PMID 27819324, 2016). "Several known stem cell markers correlated with CD47 mRNA expression in the TCGA breast carcinoma dataset including a positive correlation with cKit protein expression (p = 0.042)." (PMID 26840086, 2016). "PATZ1 mRNA expression in breast cancers negatively correlated with CD47 mRNA expression (Spearman correlation = −0.41)." (PMID 26840086, 2016). "In a subsequent study they further showed that CD47 is a strong prognostic marker for luminal-type breast cancer patients, especially in co-expression with c-Met." (PMID 26695635, 2015). "The study indicates that CD44, CD47 and c-met are the biomarkers of metastasis-initiating cells of breast cancer." (PMID 25658794, 2015). "This study shows for the first time that CD47 expression is a prognostic marker for luminal-type breast cancer patients." (PMID 25230070, 2014). "Recently, we found that MET and CD47 are co-expressed in blood circulating metastasis-initiating cells of luminal-type breast cancers." (PMID 25230070, 2014). "In conclusion, we have previously shown that circulating metastasis-initiating cells isolated from luminal breast cancer patients co-express the receptor tyrosine kinase MET as well as CD47, the ligand of SIRPalpha." (PMID 25230070, 2014). "Recent studies have shown that CD47, the ligand for SIRPα, is a prognostic factor in breast cancer and its expression correlates with SIRPα expression in bone marrow and peripheral blood of breast cancer patients." (PMID 23320069, 2013). "In the 119 clinically validated breast cancer samples, the coexpression of αvβ3 and CD47 (αvβ3+/CD47+, 0.61 ± 0.33) was more prevalent in tumor parenchymal cells (4′, 6‐diamidino‐2‐phenylindole+ (DAPI+)/CK+) compared to tumor mesenchymal cells (DAPI+/CK−, 0.30 ± 0.26) (p < 0.01, Student's t‐test)." (PMID 41168993, 2026). "As expected, CD47 expression was strongly and negatively correlated with macrophage infiltration in several cancer types, including breast cancer, melanoma, and colon cancer, consistent with its well-known function as a “don’t eat me” signal that inhibits macrophage-mediated phagocytosis." (PMID 41601654, 2026). "Notably, high CD47 expression correlates with poor responses to trastuzumab in breast cancer patients, likely due to tumor immune evasion via the CD47-SIRPα axis." (PMID 40568594, 2025). "This SIRPα-induced CD47 signaling in breast carcinoma cells may limit the efficacy of SIRPα decoy therapeutics intended to stimulate innate antitumor immune responses." (PMID 38495618, 2024). "Another application of targeting CD47 protein in breast cancer therapy may be found by eliminating aggressive radioresistant cancer cells." (PMID 38892394, 2024). "The use of CD47 blockade with radiotherapy for breast cancer BM is already being explored." (PMID 39695143, 2024). "Furthermore, in breast cancer cells, CD47 participates in Gi-mediated caspase-independent cell death." (PMID 39039207, 2024). "However, overexpression of CD47 has been discovered in numerous solid tumors and hematologic malignancies, for example, breast cancer, non-small cell lung cancer (NSCLC), and lymphoma, which can lead to immune escape and forecasts poor outcomes." (PMID 39335665, 2024). "Inhibition of CD47 expression can enhance the anti-tumor immunity of breast cancer." (PMID 39697556, 2024).
breast carcinoma (continued). "The trial is currently in the recruiting stage, and as it progresses, it may provide valuable insights into the synergy between DS-8201 and CD47 inhibition as a potential treatment approach for breast cancer and other malignancies." (PMID 39093344, 2024). "Breast cancer cells can overexpress CD47 as a means to evade the immune system." (PMID 39040452, 2024). "It has been noted that CD47 in high levels on the exosomes of breast cancer patients may be unfavorable when it comes to the course of the disease." (PMID 38892394, 2024). "Altogether, these findings demonstrate that combined targeting of CD47 and PD‐L1 via CD47 × PD‐L1 BisAb is an effective treatment for controlling AT3‐OVA breast cancer and is superior to anti‐PD‐L1 monotherapy for promoting robust CD8+ T‐cell responses within the tumor." (PMID 39584189, 2024). "Thus, coordinated effects of CD47, TAMs, and TILs appear to enable lymphatic and blood vessel invasion and breast cancer progress." (PMID 36598153, 2023). "Blocking the CD47/SIRPα pathway had promising results in treatment of several solid tumors and hematological cancers such as glioblastoma, lymphoma, and breast cancer and may compel TAMs to phagocytose tumor cells." (PMID 38033495, 2023). "Moreover, the expression intensity of CD47 in malignant meningioma (WHO grade III) was similar to that of breast cancer and lung cancer, which was considered to be highly expressed." (PMID 37171006, 2023). "This study demonstrates an association of concurrent high CD47 tumor cell expression and high CD68 macrophage counts with various TIL subsets, blood vessel invasion (CD31 positive), other aggressive tumor features, and interval‐presenting breast cancer." (PMID 36598153, 2023). "Although the 4T1 breast carcinoma model is not optimal for studying adaptive antitumor immunity, the synergy between CD47 blockade and chemotherapy response in this model suggests the relevance of CD47 as a therapeutic target for overcoming treatment resistance in breast cancer." (PMID 36768931, 2023). "Our findings support that CD47 is a multifaceted actor in the tumor microenvironment and might represent a potentially relevant treatment target in breast cancer." (PMID 36598153, 2023). "Furthermore, anti-CD47 monoclonal antibodies were shown to work synergistically with trastuzumab to improve neutrophil ADCC against breast cancer cell lines." (PMID 35865547, 2022). "Furthermore, in silico analysis of the Cancer Genome Atlas (TCGA) and METABRIC data sets from thousands of patients with breast cancer revealed that CD47 expression positively correlates with SNAI1 and Vimentin." (PMID 35575054, 2022). "We provided evidence that CD47 is upregulated in different EMT‐activated human breast cancer cells." (PMID 35575054, 2022). "Moreover, in Her2/neu+ breast cancer patients treated with trastuzumab plus vinorelbine, the expression level of CD47 was negatively correlated with the pathological response to treatment, and CD47 was significantly reduced in the complete responders." (PMID 35860564, 2022). "Radioresistant breast cancer cells are eliminated when CD47 and HER2 are blocked." (PMID 36303138, 2022). "Nevertheless, CD47 has been demonstrated to be upregulated in breast cancer by super-enhancer." (PMID 34718356, 2022). "CD47 overexpression has been reported in various human malignancies including non-Hodgkin lymphoma, stomach cancer, oral squamous cell carcinoma, lung cancer, breast cancer, and hepatocellular carcinoma and has been correlated with adverse prognosis." (PMID 36291980, 2022). "Strategies targeting the CD47-SIRPα axis demonstrate promising results for breast cancer treatment." (PMID 35860564, 2022). "In addition, the miR-708/CD47 signaling pathway was found to play a crucial role in breast cancer stem cell-like phenotypes and drug resistance." (PMID 34768921, 2021).
breast carcinoma (continued). "In addition, incubation of breast cancer cells with a CD47 agonist peptide (4N1K) derived from TSP-1 induces apoptosis in a dose-dependent manner." (PMID 34195295, 2021). "TSP1 induced CD47-dependent death of T lymphoma and breast carcinoma cells." (PMID 33925464, 2021). "In addition, CD47 has been shown to have increased expression on HR+ breast cancer cells following hypoxia." (PMID 34135901, 2021). "A study on breast cancer stem cells conveyed that metformin could indirectly affect immune-related genes such as cluster of differentiation 47 (CD47) that are involved in resistance to chemotherapy." (PMID 33849540, 2021). "High CD47 levels on the exosomes of breast cancer patients may be unfavourable 33, 34, and CD47 on the exosomes inhibits cancer cell clearance by phagocytes in pancreatic cancer 35, while it still unclear the secreted mechanism of CD47 on the exosomes." (PMID 34512146, 2021). "Indeed, we showed that macrophage-mediated phagocytosis was activated by either blocking the EMT-dependent CD47 overexpression via anti-CD47 antibody or silencing of SNAI1 or ZEB1 via siRNA in mesenchymal MDA-MB-231 breast cancer cells." (PMID 33803139, 2021). "Nonetheless, the benefits of modulating the Zeb1 transcriptional/epigenetic network in cancer immunotherapy have been clearly illustrated in the blockade of CD47, a direct transcriptional target of Zeb1, that enhances phagocytosis of breast cancer cells undergoing EMT." (PMID 33108352, 2021). "In addition, the integrin-associated protein, CD47, can also function through the Gi/o proteins to regulate breast cancer cell growth." (PMID 34343132, 2021). "For instance, CD47-blocking antibodies in combination with tumor-opsonizing antibodies significantly increased the antitumor activity of neutrophils in vitro and in vivo, whereas knockdown of CD47 increased the killing of breast cancer cells by neutrophils." (PMID 35052746, 2021). "We examined CD47 signaling in breast cancer stem cells and reached a similar conclusion." (PMID 33925464, 2021). "Thus, CD47 expression demonstrated in the radiation-surviving HER2-expressing breast cancer cells supports the concept that both anti- and pro-tumor immune factors can be enhanced by tumor cells treated by radiotherapy." (PMID 32929084, 2020). "Similarly, we recently demonstrated that the parallel assessment of innate (CD47) and adaptive (PD-L1) immune checkpoints on CTCs has significant prognostic and predictive implications in breast cancer." (PMID 32545559, 2020). "Interestingly, hypoxia – acting via HIF-1 – directly upregulated CD47 expression in breast cancer cells, while a survey of TCGA database of breast cancers found a positive correlation between CD47 and HIF target gene expression." (PMID 33224442, 2020). "However, in addition to enhancing tumor phagocytosis, blocking CD47 also improves the antigen presentation by DCs and inhibits the aggressive phenotype of breast cancer stem cells (BCSCs) via inhibition of EGFR signaling." (PMID 32929084, 2020). "We hypothesize that MYC downregulation of Cd47 may contribute to the M1/M2 shift in our models of breast cancer." (PMID 32685002, 2020). "Increasing body of evidence shows the overexpression of CD47 in a variety of tumors, e.g., anaplastic thyroid carcinoma, esophageal squamous cell carcinoma, glioblastoma, T cell lymphoblastic leukemia, and bladder and breast cancer." (PMID 31277366, 2019). "However, the exact mechanism of CD47 overexpression in breast cancer solid tumors still unclear, which needs to be evaluated in the future study." (PMID 31528120, 2019). "For example, CD47 is highly expressed in breast cancer tissue samples." (PMID 31100935, 2019). "For example, the protective autophagy response in non-transformed CD47-deficient cells exposed to ionizing radiation manifests as a non-protective mitophagy response in breast cancer cells." (PMID 31632920, 2019).
breast carcinoma (continued). "Therefore, given the close relationship between the clinical behaviour and the CSCs prosperity of breast cancer, our result opens an avenue to develop new therapeutic strategies targeting the miR‐708/CD47 axis." (PMID 31273952, 2019). "What is more, the expression of CD47 was elevated in breast cancer patients with poor prognosis, then incorporating CD47 into our clinicopathological staging system may be useful in future." (PMID 31273952, 2019). "As validated in this study, CD47 has shown high levels of expression on breast cancer cells, including triple negative breast carcinoma cells, and could serve as a valuable biomarker to target for both imaging and therapy." (PMID 30463284, 2018). "FACS analysis showed that CD47-labeled SERS nanoparticles bound to seven different breast cancer cell lines at levels 12-fold to 70-fold higher than isotype control-labeled nanoparticles (p < 0.01), suggesting that our CD47-targeted nanoparticles actively bind to CD47 on breast cancer cells." (PMID 30463284, 2018). "Since our SERS nanoparticles are also fluorescently labeled, FACS analysis may be utilized to determine the binding levels of our CD47 antibody-labeled SERS nanoparticles to various breast cancer cell lines in vitro." (PMID 30463284, 2018). "In this study, we investigated the expression level of CD47 on several breast cancer cell lines to evaluate if it could be a useful breast tumor target for our SERS nanoparticle imaging strategy." (PMID 30463284, 2018). "Interestingly, a recent study revealed that the expression of CD47 is transcriptionally regulated in breast cancer cells by HIF1α." (PMID 29707136, 2018). "Besides antibodies, thrombospondin (TSP) is the only natural ligand for CD47 shown to induce apoptosis of breast cancer cells." (PMID 29748606, 2018). "A recent study from Semenza’s group showed that HIF-1α activated transcription of CD47 in mesenchymal triple-negative primary breast cancer cells (SUM159) and promoted the breast cancer stem cell phenotype, which further protected cancer cells from phagocytosis by bone marrow-derived macrophages." (PMID 30061885, 2018). "Furthermore we showed, by perturbing the TNF-NFKB1 pathway, that reduction of CD47 expression leads to increased phagocytosis of MCF7 breast cancer cells." (PMID 28378740, 2017). "To locate the upstream pathways that are responsible for the upregulation of CD47 through the binding and activation of distal cis-regulatory regions, we focused first on finding candidate transcription factors that bind to the breast cancer specific constituent, E5." (PMID 28378740, 2017). "Altogether, these data suggest that the transcription factors STATs 3, 5, 6, NFKB and/or PPAR could be key for the activation of CD47 expression by binding to E5 in MCF7 breast cancer cells." (PMID 28378740, 2017). "Targeting CD47 is in the spotlight of immunotherapy in lung and breast cancer." (PMID 29027943, 2017). "In T-ALL and breast cancer cells, CD47 is associated with an SE that is not present in CD3+ T cells or mammary epithelial cells, respectively." (PMID 28378740, 2017). "From the healthy control samples, CD47 expression was remarkably detected in ~10% of individual circulating exosomes whereas minimal CD47 expression (0.7%, after deducting the background signal) was shown in the circulating exosomes from breast cancer patients." (PMID 27819324, 2016). "Therefore, we excluded other forms of breast cancer and reexamined the correlation between CD47 expression and survival in TNBC." (PMID 26840086, 2016). "Because basal breast carcinomas were previously reported to express higher CD47 and have a poorer prognosis, we were concerned that the correlation between survival and CD47 expression may be an artifact of breast cancer heterogeneity." (PMID 26840086, 2016).